PRDX5 (peroxiredoxin 5)
Diseases named in the same sentence as PRDX5 in open-access papers (continued):
Sharing a sentence is not in itself a finding about the gene and the disease.
gouty arthritis (1 paper, 2023). "Based on the anti-inflammatory function of MaR1 and Prdx5 in vitro, we investigated whether MaR1 treatment or Prdx5 deficiency influenced the severity of MSU crystal-induced gouty arthritis in vivo." (PMID 37996809, 2023). "Our study provides a new strategy by which Prdx5 may help prevent acute gout attacks." (PMID 37996809, 2023).
hypersomnia (1 paper, 2023). A sleep disorder characterized by excessive sleepiness. "Six (GPX4, PSMB5, PSMB6, PRDX5, ASNA1, EIF4H) out of seven hub genes were associated with the expression of insomnia/hypersomnia only in females, while UROD was the only hub gene common to both sexes." (PMID 37884562, 2023).
Impaired glucose tolerance (1 paper, 2025). An abnormal resistance to glucose, i.e., a reduction in the ability to maintain glucose levels in the blood stream within normal limits following oral or intravenous administration of glucose. "Simultaneously, altered bile acid metabolism (via PRDX5) and impaired glucose tolerance in PCOS mice suggest that metabolic dysfunction may result from and exacerbate these hormonal imbalances." (PMID 40950398, 2025).
kidney cancer (1 paper, 2021). Primary or metastatic malignant neoplasm involving the kidney. "Increased or decreased levels of PRDXs mRNA expression levels were found among 33 tumor types, such as PRDX1, PRDX2, PRDX4 and PRDX5 increased in several cancer types, while PRDX3 and PRDX6 decreased in there types of kidney cancer (KIRP, KIRC and KICH)." (PMID 34246267, 2021). "Notably, when compared to adjacent or normal tissues, PRDX1, PRDX2, PRDX4 and PRDX5 were significantly up-regulated expression in several cancer types (UCEC, READ, BLCA, BRCA, CHOL, COAD, LIHC, THCA), while PRDX3 and PRDX6 were down-regulated expression in kidney cancers." (PMID 34246267, 2021).
liver disease (1 paper, 2025). "Substantial evidence indicates that Prdx5 plays an important role in various diseases, including liver disease and non-small-cell lung cancer." (PMID 39747444, 2025).
liver failure (1 paper, 2023). A liver disease characterized by the liver losing or has lost all of its function. "Next, we sought to evaluate the upstream mechanism(s) governing the dysregulation of ABHD10 and S-palmitoylated PRDX5 in the context of AH-related liver failure." (PMID 37400491, 2023).
Lung diseases (1 paper, 2022). "Lung diseases are caused by several factors, including ROS, which are closely associated with PRDX5 function." (PMID 35546738, 2022).
male infertility (1 paper, 2024). The inability of the male to effect fertilization of an ovum after a specified period of unprotected intercourse. "Our findings demonstrate for the first time, an association between PRDX5 expression and idiopathic primary male infertility." (PMID 39726694, 2024). "This study offers mitochondrial pathology as the underlying etiology of idiopathic male infertility and suggests an association with the downregulated expression of mitochondrial PRDX5 and SOD2." (PMID 39726694, 2024). "In our proteomics analysis, SOD2 and PRDX5 were underexpressed, while GSR was overexpressed, underscoring their potential significance in the pathophysiology of male infertility." (PMID 39726694, 2024). "Specifically, three mitochondrial proteins (GSR, PRDX5, and SOD2) exhibited expression patterns that have not been previously documented in the context of male infertility." (PMID 39726694, 2024).
mastitis (1 paper, 2021). Inflammation of breast tissue during lactation or postpartum due to an obstructed duct or infection. "In addition, the PRDX5 gene expression is increased in mastitis sheep milk." (PMID 34691146, 2021).
oral squamous cell carcinoma (1 paper, 2022). "PRDX4 is a metastasis-related marker in oral squamous cell carcinoma, and high PRDX5 expression correlates with a poor prognosis." (PMID 35350568, 2022). "PRDX4 has been reported to promote progression of oral squamous cell carcinoma; however, the biological role of PRDX5 in HNSCC is unknown." (PMID 35350568, 2022).
peritonitis (1 paper, 2023). Inflammation of the peritoneum (tissue that lines the abdominal wall and covers most of the organs in the abdomen). "We further explored the function of MaR1 and Prdx5 in a model of MSU crystal-induced peritonitis." (PMID 37996809, 2023).
preeclampsia (1 paper, 2015). Preeclampsia is a hypertensive disorder of pregnancy that is characterized by new-onset hypertension with proteinuria presenting after 20 weeks of gestation, and depending on mild or severe forms may initially present with severe headache, visual disturbances, and hyperreflexia. "RT-qPCR confirmed aberrant expression of genes involved in inflammation and stress response (TLR4 and TLR9) and also genes involved in host defense (PRDX5, MIF, CD74, NFE2L1, and CSF3R), suggesting that preeclampsia sera suppress the TLR4/9-dependent excess oxidative stress in adipose tissue." (PMID 26089598, 2015).
prostate tumors (1 paper, 2024). "Furthermore, Prdx5+/−;MYCT mice were slower in the emergence of ENZ resistance and significantly inhibited the growth of prostate tumors." (PMID 38115765, 2024).
SARS-CoV infection (1 paper, 2020). "Downregulation of peroxiredoxin 5 (PRDX5) gene levels by SARS-CoV infection in the 2B4 cell line reduces the intracellular hydrogen peroxide (H2O2) levels to minimize oxidative stress in the infected cells." (PMID 32754004, 2020).
serous ovarian cancer (1 paper, 2018). "High PRDX5 mRNA expression was associated with a poorer OS for serous ovarian cancer patients and endometrioid cancer patients." (PMID 30104402, 2018).
tick-borne diseases (1 paper, 2022). "4-HNE, generated during tick-borne diseases, also binds to other metabolically important proteins, including GSH transferase, ANGPT4, clathrin, PDIA3, actinin-4, and PRDX5." (PMID 35457192, 2022).
cancer (112 papers, 2005 to 2026). A tumor composed of atypical neoplastic, often pleomorphic cells that invade other tissues. "In the context of cancer, PRDX5 is often linked to poor disease outcomes." (PMID 40597205, 2025). "The upregulated expression of Prdx3 and Prdx5 is associated with the development of chemoresistance in different cancers and selective targeting of these mitochondrial Prdxs can lead to sensitization of cancer cells to chemotherapy." (PMID 31500275, 2019). "However, an increased production of Prdx3 and Prdx5 is associated with the development of chemoresistance in certain types of cancers and it leads to further complications in cancer treatment." (PMID 31500275, 2019). "The results unveil a novel PRDX5/GPX4/SIAH2/WSB1 signaling axis as a promising therapeutic vulnerability for cancer." (PMID 40831323, 2025). "In conclusion, the results suggest that okanin targets PRDX5, which capacitates it for anti‐cancer activity via apoptosis and ferroptosis independently." (PMID 40831323, 2025). "To understand the role of H2O2 release from cancer cell mitochondria in terms of its effects on cell signaling, proliferation, and tumor growth, we stably expressed an H2O2 scavenger—peroxiredoxin-5 (Prdx5)—in the IMS in two human cancer cell lines." (PMID 36935009, 2023). "As ROS-induced cytotoxicity is the central element of chemo- and radiotherapies, the increased levels and activity of antioxidant enzymes—including Prdx5—play an important role in determining the chemo- and radio-resistance of cancer cells." (PMID 37443747, 2023). "Recombinant human peroxiredoxin-5 (hPRDX5), isolated from anti-cancer bioactive peptide (ACBPs), shows a homology of 89% with goat peroxiredoxin-5 (gPRDX5) and is reported to display anti-tumor activity in vivo." (PMID 36102418, 2022). "Some research indicated that PRDX5 expression was closely related to cancer cell proliferation, signal transduction, and metastasis." (PMID 37305326, 2022). "Our survey of studies analyzing the involvement of mitochondrial Prdxs in human cancers shows that most of the conducted studies are based on the expression analysis of Prdx3 and Prdx5." (PMID 31500275, 2019). "Goat peroxiredoxin-5 (gPRDX5) was verified as a good anti-cancer bioactive peptide (ACBP) against different tumor cell lines." (PMID 28423711, 2017). "The goat peroxiredoxin-5 (gPRDX5) is an anti-cancer bioactive peptide (ACBP), which was first identified by Xiulan Su from goat spleen or liver which was immunized with human gastric cancer protein extract." (PMID 28423711, 2017). "Importantly, PRDX5 overexpression in cancer cells helps in scavenging excess ROS production and, therefore, plays a tumorigenic role." (PMID 40597205, 2025). "In colorectal HCT116 cancer cells, okanin binds directly to peroxiredoxin 5 (PRDX5) at a site opposite the catalytic domain, which directly inhibits the enzymatic activity and triggers the production of reactive oxygen species, leading to independent apoptosis and ferroptosis." (PMID 40831323, 2025). "Many types of malignant tumors can observe the abnormal expression of PRDX5." (PMID 37305326, 2022). "We hypothesized that PRDX5 promotes cancer by targeting the levels of ROS because the expression of PRDX5 and the content of ROS generation in HepG2 cells were inversely correlated." (PMID 36118528, 2022). "In microenvironmental stress conditions, such as hypoxia, E-twenty-six transcription factor 1 and 2 (Ets1/2), and high-mobility-group protein B1 (HMGB1), mediate the upregulation Prdx5 in cancer cells, particularly in human prostate and epidermoid cancer cells exposed to H2O2 or hypoxia." (PMID 31500275, 2019). "Like Prdx3, the up- and downregulation of Prdx5 is also observed in many types of cancers." (PMID 31500275, 2019). "Moreover, PRDX5 over-expression could reverse the anti-cancer effects induced by β-CCE in HepG2 cells." (PMID 36118528, 2022).
cancer (continued). "The second subnetwork containing 13 nodes and 12 edges showed the interaction between PRDX2 and TAGLN2 as well as a mild increase in multiple components of the peroxisome (SOD1, CAT, PRDX5, PRDX1) and proteoglycans in cancer (FLNA, STAT3)." (PMID 38322285, 2023). "To avoid these issues, we targeted Prdx5, a hydrogen peroxide scavenger, to the IMS of tumor cell mitochondria to determine the significance of mitochondrial ROS signaling for cancer cell proliferation, survival, and in vivo tumor growth." (PMID 36935009, 2023). "PRDX5, the fifth member of the PRDX family, is located in the cytoplasm and mitochondria of cells and is involved in anti-cancer and anti-inflammatory functions." (PMID 36118528, 2022). "All these results suggested that the NEMO/IKKΒ complex was the likely target through which SHK exerts its anti-cancer activity, rather than PRDX5." (PMID 35260565, 2022). "The results showed that the expression of PRDX5 increased significantly in cancer samples than that of in the non-tumorous samples, and the same trend of Nrf2 and NQO1 protein levels compared to the adjacent normal ones." (PMID 31899687, 2020). "Finally, we sought to assess whether okanin targets at PRDX5 to inhibit cancer cell growth in nude mice model, for which we generated a stable PRDX5‐overexpressing cell line, hereby designated HCT116‐PRDX5 O.E. and the wild type cells as HCT116‐WT." (PMID 40831323, 2025).
tumor (63 papers, 2009 to 2026). "This study offers new evidence for determining that the expression of PRDX5 is associated with advanced tumor grade, poor prognosis, and suboptimal response to multiple therapies in PCa within the PRDXs family." (PMID 40281661, 2025). "In conclusion, this study offers new evidence for determining that the expression of PRDX5 is associated with advanced tumor grade, poor prognosis, and the suboptimal response to multiple therapies in PCa within the PRDXs family." (PMID 40281661, 2025). "PRDX5 relates to cell proliferation, differentiation, and cell signal transduction, and is closely associated with tumor size, lymphatic invasion, and drug resistance." (PMID 37305326, 2022). "The next study showed that PRDX5 and Nrf2 expressions were tightly associated with tumor size, clinical TNM stage, lymph node infiltration, differentiation and Ki-67 expression." (PMID 31899687, 2020). "The expression of Prdx3 and Prdx5 in different types of malignancies involves their association with different factors, such as transcription factors, micro RNAs, tumor suppressors, response elements, and oncogenic genes." (PMID 31500275, 2019). "In addition, several proteins such as enolase, vimentin, peroxiredoxin 5, Hsp 70, periostin precursor, RhoA, cathepsin D preproprotein, and annexin 1 were found to be associated with the tumor responses to treatment within each subtype." (PMID 22110952, 2011). "In tumor biopsies, studies of other peroxiredoxins, such as peroxiredoxin 5 or peroxiredoxin 1 have demonstrated that their expression before any treatment is able to predict clinical outcomes." (PMID 41187427, 2025). "Since mitochondria and peroxisomes are the main sources of ROS/reactive nitrogen species within cells, recent studies have highlighted the upregulation of PRDX5 in various tumor tissues, enhancing tumorigenic phenotypes and metastatic potential." (PMID 40281661, 2025). "According to previous studies, lower Prdx5 levels also correlate with slow tumor growth and reduced infiltration and metastasis capability." (PMID 37443747, 2023). "Results have revealed that approximately two thirds of NSCLC patients exhibit demethylation in the Prdx5 promoter region in a ROS-dependent manner, and this process is also related to tumor progression status (TNM stage)." (PMID 37443747, 2023). "After treatment period of 25 days cycle, the tumor volumes of Nrf2 and PRDX5 shRNA group were significantly decreased than that of the other groups and weights of the corresponding tumor were also the smallest (*P < 0.05, **P < 0.01)." (PMID 31899687, 2020). "The nude mice were anesthetized when tumor volume gained to about 100 mm3, treated with Nrf2 and/or PRDX5 shRNA." (PMID 31899687, 2020). "PRDX5 inhibitory drug suppresses CRPC tumor growth in mice and stabilizes CRPC tumors in patients." (PMID 38115765, 2024). "In addition, the expression of PRDX2 and PRDX5 in the GPx2 KD tumor was increased by 1.3-fold (logFC = 0.4) and catalase by 1.2-fold (logFC = 0.27), whereas the expression of SOD2 was unchanged." (PMID 35193955, 2022). "In addition, PRDX5 mRNA expression was observed to be incrementally up-regulated with normal and tumour tissues analysed in the TNMplot database (p = 1.21e-53)." (PMID 36118528, 2022). "Furthermore, with the progress of clinical tumor staging, the expression of PRDX5, Nrf2, and Ki67 was highly positive." (PMID 37305326, 2022). "Furthermore, the PC inhibitor (C35H55N15O4) recruited macrophages into the tumor, such as CCL6 and PRDX5, by secreting several immune factors with anti-tumor effects." (PMID 36476230, 2022). "Furthermore, we will use zebrafish to gene edit PRDX5 or Nrf2 loci and then microinject tumor cells." (PMID 37305326, 2022). "Higher levels of PRDX5 in hormone-receptor-negative tumors have been associated with tumor-node metastasis, higher tumor volumes, and shorter survival." (PMID 31987042, 2020).
tumor (continued). "Moreover, PRDX-1,3,4 and 5 were found to be expressed in more than 80% of breast cancer cases, and the expression of PRDX5 was related to tumor size and lymph node metastasis." (PMID 31899687, 2020). "Since the study showed high expression of PRDX5 and Nrf2 tightly associated with tumor size, clinical TNM stage, lymph node infiltration, etc, and predicted poor prognosis, we used Nrf2 and PRDX5 shRNA as therapeutic targets for tumor growth in vivo and achieved good results." (PMID 31899687, 2020). "Integrating with the bioinformatics analysis, high expression of PRDX5 may enhance energy supply for tumor cells, thereby promoting cell cycle progression, which indicates that the metabolism impact of ROS or PRDXs family in PCa may merit further investigation." (PMID 40281661, 2025). "Furthermore, PRDX5 actives the Nrf2 signaling pathway, which could protect tumor cells from anti-tumor immunity." (PMID 35350568, 2022). "In mice inoculated with either HCT116‐WT or HCT116‐PRDX5 O.E. cells, okanin injection i.p. downregulated the protein levels of both PRDX5 and GPX4 in all tumor tissues." (PMID 40831323, 2025). "We noticed that Prdx5+/−;MYCT mice, compared to MYCT, had significantly delayed prostatic intraepithelial neoplasia (PIN)/tumor progression in terms of tissue weight and histopathology." (PMID 38115765, 2024). "Compared with normal tissues, six proteins (GALNT6A, FOXO1, ACSM3, DNAJA1, PRDX5, and SERPINB9) were notably overexpressed in tumour tissues." (PMID 39030559, 2024). "We targeted Prdx5 to the mitochondrial IMS-Prdx5 in order to scavenge H2O2 arising from the ETC, to determine the effect of these signals on HIF activation in tumor cells." (PMID 36935009, 2023). "To study clinical correlation, we first analyzed Nrf2, PRDX5 and NQO1 mRNA expression in both tumor tissues and the adjacent normal tissues, and the results showed upregulated these mRNAs in tumors." (PMID 31899687, 2020). "Other tumor suppressor genes such as FOXO transcription factors, function by activating many antioxidant genes, such as Prdx3 and Prdx5." (PMID 31500275, 2019). "Furthermore, except for PRDX5, all PRDX genes exhibited a trend of significantly elevated expression as tumor progression and lymphatic metastasis occurred." (PMID 40303499, 2025). "Also, miR-143-3p tumor suppressor was identified as PCAT6 downstream target miRNA, which directly regulates, PRDX5 (peroxiredoxin 5)." (PMID 37386429, 2023). "The current preclinical model may not fully mirror the complexity of human tumor microenvironments where PRDX5 engages dynamic redox networks." (PMID 40831323, 2025). "We proved that the synergy of PRDX5 and Nrf2 could play an essential role in regulating the proliferation, drug resistance, and mechanism of NSCLC tumors in vivo and also consistent with LIOTTA’s research, ROS levels could lead to enhanced tumor cell metastasis." (PMID 37305326, 2022). "However, no expressional significance of PRDX3 (p=0.150) and PRDX5 (p=0.322) was shown, consistent with their expressional differences between all the tumor samples and the normal controls in TCGA-COAD dataset via TIMER, indicating the reliability of the paired samples T tests." (PMID 32231717, 2020). "The results demonstrated that PRDX1, PRDX4, PRDX5 and PRDX6 were significant difference between tumor and normal tissues, which were also validated in HPA database." (PMID 34246267, 2021).
infection (19 papers, 2007 to 2025). The state of being infected such as from the introduction of a foreign agent such as serum, vaccine, antigenic substance or organism. "Moreover, PRDX5 has been negatively linked to pro-inflammatory JNK signaling leading to decreased resistance to infection in drosophila." (PMID 29422028, 2018). "We found similar evidence of increased effects among individuals with past infection for one pathogenic protein (ITGB6) elevated with LRTIs, and another (PRDX5) increased with skin and subcutaneous infections." (PMID 39143319, 2024). "Based on the our assumption that AAV can provoke oxidative stress in MSC, we analyzed the mRNA expression of two antioxidant enzymes: Peroxiredoxin 5 (PRDX5) and Mn superoxide dismutase (SOD2), SERPINB2 and HSP90 in human MSC after 7 days post infection." (PMID 34494647, 2021). "Notably, infection-induced dysregulation of immune-related genes (e.g., TXNIP, HO-1 and Prdx5) has been reported, while deletion of the gntR10 gene elevates levels of TNF-α, IL-6 and IL-8 transcripts in infected cells." (PMID 41235247, 2025).
kidney disease (3 papers, 2016 to 2025). "Rather, there is a report that the decrease in Prdx5 expression is associated with renal disease." (PMID 39857434, 2025). "Based on these findings, we explored the therapeutic potential of Prdx5 as a means of limiting the progression of kidney disease." (PMID 26872211, 2016).